ESRRA (estrogen related receptor alpha)
Description:
Binds to an ERR-alpha response element (ERRE) containing a single consensus half-site, 5'-TNAAGGTCA-3'. Can bind to the medium-chain acyl coenzyme A dehydrogenase (MCAD) response element NRRE-1 and may act as an important regulator of MCAD promoter. Binds to the C1 region of the lactoferrin gene promoter. Requires dimerization and the coactivator, PGC-1A, for full activity. The ERRalpha/PGC1alpha complex is a regulator of energy metabolism. Induces the expression of PERM1 in the skeletal muscle.
Synonyms: ERR1; ESRL1; NR3B1; ERRalpha; ERRa
Tractability: Small molecule: a structure with a bound ligand is known; a high-quality ligand is known; it has a binding pocket of medium quality; it belongs to a druggable protein family. PROTAC: it is named in the literature on targeted protein degradation; UniProt records ubiquitination sites on it; ubiquitination databases record sites on it; a small molecule that binds it is known.
Target class: Nuclear hormone receptor subfamily 3 group B member 1; Transcription factor; Nuclear receptor; Nuclear hormone receptor subfamily 3 group B; Nuclear hormone receptor subfamily 3
Gene: Protein-coding gene on chromosome 11 (64,305,080 to 64,316,744, forward strand). Ensembl gene ENSG00000173153.
Subcellular location: Nucleus; Cytoplasm
Subcellular location (Human Protein Atlas): Nucleoli fibrillar center; Nucleoplasm; Cytokinetic bridge; Microtubules; Mitotic spindle; Primary cilium
Pathways (Reactome):
Gene expression (Transcription): Nuclear Receptor transcription pathway; Regulation of RUNX2 expression and activity
Metabolism: PPARA activates gene expression
Organelle biogenesis and maintenance: Transcriptional activation of mitochondrial biogenesis
Gene Ontology:
Molecular function: DNA-binding transcription factor activity; protein binding; protein domain specific binding; sequence-specific DNA binding; sequence-specific double-stranded DNA binding; DNA-binding transcription factor activity, RNA polymerase II-specific; estrogen response element binding; nuclear receptor activity; DNA binding; DNA-binding transcription activator activity, RNA polymerase II-specific; DNA-binding transcription repressor activity, RNA polymerase II-specific; nuclear steroid receptor activity; RNA polymerase II cis-regulatory region sequence-specific DNA binding; steroid binding; zinc ion binding
Biological process: regulation of DNA-templated transcription; positive regulation of transcription by RNA polymerase II; regulation of transcription by RNA polymerase II; intracellular receptor signaling pathway; negative regulation of transcription by RNA polymerase II; nuclear receptor-mediated steroid hormone signaling pathway
Cellular component: cytoplasm; fibrillar center; nucleoplasm; nucleus; chromatin
Genetic constraint (gnomAD): Loss-of-function variants: 7 observed, 28.68 expected, observed/expected ratio (o/e) 0.24, 90% interval 0.14 to 0.46. The upper end of that interval is the gene's LOEUF score, 0.46, which puts it in group 2 of 6, group 1 being the genes least tolerant of losing a copy. Missense variants: 378 observed, 517.92 expected, observed/expected ratio (o/e) 0.73, 90% interval 0.67 to 0.8. Synonymous variants: 223 observed, 234.7 expected, observed/expected ratio (o/e) 0.95, 90% interval 0.85 to 1.06.
Homologues: Orthologues: chimpanzee ESRRA (99% identical), dog ESRRA (99% identical), macaque ESRRA (99% identical), pig ESRRA (99% identical), guinea pig ESRRA (99% identical), mouse Esrra (98% identical), rat Esrra (98% identical), zebrafish esrra (65% identical), Drosophila melanogaster ERR (42% identical). Paralogues in human: ESRRB (60% identical), ESRRG (60% identical), ESR2 (34% identical), ESR1 (34% identical), NR3C2 (28% identical), NR3C1 (28% identical), PGR (28% identical), AR (24% identical).
Diseases named in the same sentence as ESRRA in open-access papers:
ESRRA is named in the same sentence as 171 diseases in open-access papers, as found by Europe PMC text mining. Sharing a sentence is not in itself a finding about the gene and the disease. The quoted sentences say what the papers report.
breast cancer (149 papers, 2009 to 2026). A primary or metastatic malignant neoplasm involving the breast. "For example, the chromosomal loops on chr11 are complemented by the binding of CTCF, FOXA1, and ESRRA, molecules with potential roles in breast cancer risk." (PMID 37541849, 2023). "ESRRA is overexpressed in a variety of cancers, including breast cancer, and is associated with recurrence, poor prognosis, and tamoxifen/fulvestrant treatment response." (PMID 36142451, 2022). "The nuclear receptor, estrogen-related receptor alpha (ERRα), plays an important role in breast cancer cell metabolism, and its overexpression has been linked to poor survival." (PMID 32717915, 2020). "The homozygous deletion of ESRRA in a mouse model of ERBB2-induced mammary tumors causes a significant delay in tumor development." (PMID 26639757, 2015). "Moreover, the epidermal growth factor/Erb-B2 receptor tyrosine kinase 2 (EGF/ERBB2) signaling pathway in breast cancer cells modulated the transcription activity of ESRRA, which was associated with poor prognosis in breast and ovarian cancers." (PMID 36517562, 2022). "In breast cancer cells, Estrogen-Related Receptor alpha (ERRα) regulates gene expression and transcription through two primary mechanisms." (PMID 41246358, 2025). "While ESRRA is recognized for its role in various cancers, including breast cancer 46, glioma 47, and gallbladder cancer 48, its regulation of DSN1 provides a mechanistic link between this transcription factor and the cell cycle machinery." (PMID 40535813, 2025). "Estrogen-related receptor alpha (ERRα) has been identified as a key player in the development of obesity-related tumors, including breast cancer." (PMID 39624081, 2024). "Recently, estrogen-related receptor alpha (ERRα) was shown to inhibit metastasis progression of breast cancer cells by activating immune response in the bone." (PMID 35994202, 2022). "Inhibition of estrogen-related receptor alpha (ERR-α) reduced pyruvate entry into mitochondria by blocking the expression of MPC1 in breast cancer cell lines." (PMID 33473180, 2021). "For example, in breast cancer, studies showed that chemical or estrogen-related receptor alpha (ERRα)-mediated disruption of the MPC inhibited proliferation in cell lines." (PMID 34503089, 2021). "It has been reported that ESRRA over-expression is related to poor prognosis in various cancers, such as breast cancer 6, glioma 7 and gallbladder cancer 8, via accelerating cancer cell growth and enhancing migration and invasion capacity." (PMID 34131395, 2021). "Recently, it has been reported that estrogen-related-receptor alpha (ERRα), an important factor of cancer cell invasiveness, promotes breast cancer cell dissemination from primary mammary tumors to the bone." (PMID 32850393, 2020). "In breast cancer, several studies show that chemical or estrogen-related receptor alpha (ERRα)-mediated disruption of the MPC inhibits proliferation in cell lines." (PMID 32784379, 2020). "ESRRA regulates the expression of genes that allow utilization of lactate as an energy source, which enables breast cancer cells to adapt to extended periods of glucose deprivation." (PMID 30072418, 2019). "We established for the first time that estrogen-related receptor alpha (ERRα) is a transcription factor involved in the higher activation of the human ACSL4 promoter in breast cancer cells." (PMID 31311992, 2019). "Increasing evidences suggested that the expression of estrogen-related receptor alpha (ERRα) was correlate with unfavorable clinical outcomes of breast cancer patients." (PMID 26871469, 2016). "Both of these nuclear receptors have increased expression in breast cancer and ovarian cancer, while in neuroblastoma ESRRA expression has been shown to increase HIF2A expression and correlates with poor survival." (PMID 27128972, 2016).
breast cancer (continued). "Finally, we explored the expression differences among various solid tumors and found that ESRRA expression level in gastric cancer is generally higher than colorectal adenocarcinoma, breast cancer and lung cancer according to Jaiswal Multi-cancer Statistics." (PMID 34131395, 2021). "Another in vivo study suggests that the tumor-promoting effects of the Estrogen-Related-Receptor-Alpha (ERRα) in breast cancer may be mediated in part via OPG." (PMID 26054853, 2015). "Likewise, the mTOR-dependent stabilization of the metabolic regulator estrogen-related receptor alpha (ERRα) supports lapatinib resistance in HER2-amplified breast cancer by promoting the glutathione-dependent antioxidant capacity and enhancing glutamine dependency." (PMID 34572926, 2021). "Moreover, ESRRA mediates the intrinsic resistance of breast cancer cells to PI3K/MTOR inhibitors." (PMID 30072418, 2019). "A recent study also reported that miR-137 impairs proliferation and migration of cells of a breast cancer cell line by targeting expression of the nuclear receptor estrogen-related receptor alpha (ERRα), suggesting that miR-137 may suppress the formation of breast cancer." (PMID 26215676, 2015). "GREM1-mediated EGFR activation was suggested to enhance the promoter activity of estrogen-related receptor alpha (ERRα), which is predicted to bind to the GREM1 promoter to increase GREM1 expression and drive breast cancer cell proliferation." (PMID 37615860, 2023). "We also observed coincident binding throughout the TAD of transcription factors relevant to breast cancer, including CTCF, FOXA1, ESRRA (a relative of the estrogen receptor ER), and MYC." (PMID 37541849, 2023). "Estrogen-related receptor alpha (ERR-α), an orphan receptor, augments cell proliferation and tumorigenesis in HRT-mediated breast cancer." (PMID 33499313, 2021). "In breast cancer, PGC-1α was shown to stimulate nuclear receptors and transcription factors, including PPARα, estrogen-related receptor alpha (ERRα), NRF1, and NRF2, which in turn led to increased ATP production." (PMID 32354000, 2020). "A VHL-recruiting PROTAC has been shown to degrade estrogen-related receptor alpha (ERRα) (PROTAC_ERRα, DC50 = 100 nM) with implications in breast cancer treatment." (PMID 31500395, 2019). "As a key regulator of cellular energy metabolism, estrogen-related receptor alpha (ERRα) also acts on the promoter of the S6k1 gene, inhibiting its transcription to sensitize ERα-negative breast cancers to mTORC1/S6K1 inhibitors." (PMID 35879299, 2022). "PGC-1α is a co-transcriptional regulator that induces mitochondrial biogenesis by activating transcription factors such as peroxisome proliferator-activated alpha (PPARα), estrogen-related receptor alpha (ERRα), nuclear respiratory factor 1 (NRF1), and NRF2 in breast cancer." (PMID 31552162, 2019). "ESRRA has been most studied in the context of breast cancer: it is a negative prognostic marker in ER(–) tumors, and it induces VEGF mRNA expression and contributes to the malignant phenotype of a breast cancer cell line." (PMID 21949640, 2011).
prostate carcinoma (42 papers, 2015 to 2026). A carcinoma that arises from epithelial cells of the prostate gland. "Recently, we demonstrate that the transcription factor ERG, expressed by the TMPRSS2:ERG fusion gene, can directly transactivate the ESRRA gene in advanced prostate cancer." (PMID 32226548, 2020). "It has recently been reported that the overexpression of ESRRA promotes in vitro cell proliferation and malignant growth capacities of cells from prostate cancer cell lines LNCaP and PC-3 under both normal and hypoxic conditions." (PMID 26639757, 2015). "Moreover, the expression of PGC-1α hinders prostate cancer progression by activating catabolism via estrogen-related receptor alpha (ERRα)." (PMID 34150624, 2021). "Similarly, PGC1α suppresses prostate cancer aggressiveness and metastasis by activating the estrogen-related receptor alpha (ERRα)-dependent transcriptional program or inhibiting polyamine synthesis." (PMID 33917757, 2021). "In prostate cancer, PGC-1 inhibits metastasis via estrogen-related receptor alpha (ERRα)-mediated transcriptional regulation." (PMID 33081387, 2020). "Moreover, Estrogen-Related Receptor Alpha (ERRα) can interact with HIF-1α, thereby inhibiting its ubiquitination and degradation to promote the adaptation of prostate cancer cells to hypoxic conditions." (PMID 35158804, 2022).
Obesity (26 papers, 2011 to 2026). Accumulation of substantial excess body fat. "The transcription factor estrogen-related receptor α (ESRRA) has been implicated in obesity as a regulator of mitochondrial metabolism and in the regulation of satiety." (PMID 39826697, 2025). "Here, we show that adipocyte-specific ESRRA deficiency preserves osteogenesis and vascular formation in adipocyte-rich bone marrow upon estrogen deficiency or obesity." (PMID 38704393, 2024). "To validate a role for ESRRA in promoting diet-induced obesity, we fed both WT and Esrra−/− mice a HFD." (PMID 39826697, 2025). "We also aim to elucidate ESRRA’s specific contributions to diet-induced obesity and refine our understanding of how this transcription factor influences metabolic outcomes in the context of dietary intake." (PMID 39826697, 2025). "Consistent with the findings in ESRRA null mice, ESRRA inverse agonists, compound 29 (C29) and compound 50 (C50), also show obesity resistance in DIO mouse models." (PMID 32121253, 2020). "Although confirmatory studies need to be performed in ESSRA knockout mice, it is likely that ESRRA mediates many of genistein’s beneficial effects on diet-induced obesity." (PMID 32121253, 2020). "Here, we test the hypothesis that intestinal ESRRA plays a critical role in the development of diet-induced obesity." (PMID 39826697, 2025). "However, existing studies primarily focusing on germline Esrra mutants fail to account for tissue-specific roles of ESRRA in obesity." (PMID 39826697, 2025). "Our results suggest that the transcription factor ESRRA might contribute to diet-induced obesity via its role in tissues other than the small intestine, such as adipose, muscle, and/or brain." (PMID 39826697, 2025). "These evidences indicated that adipocyte ESRRA deficiency modulates leptin level without disturbing general metabolism in the context of HFD-induced obesity." (PMID 38704393, 2024). "Similarly, increasing the expression of peroxisome proliferator-activated receptor gamma coactivator 1 alpha (PPARGC1A), the protein ligand of ESRRA, increases energy expenditure and reduces obesity." (PMID 32121253, 2020). "Surprisingly, although ESRRA regulates the mitochondrial function and lipid catabolism, ESRRA-null mice have displayed a general decrease in fat mass and resistance to high-fat diet-induced obesity." (PMID 32121253, 2020). "Since ESRRA is responsive to stress-induced metabolic challenges including overfeeding, we queried whether adipocyte-specific ablation of ESRRA is resistant to diet-induced obesity (DIO) or involved in fat-bone axis." (PMID 38704393, 2024). "When the phenotypes of high-fat diet-induced obese (DIO) mice were compared with high-fat diet-induced obesity-resistant (DIO-R) mice, the DIO-R mice had significantly higher levels of AMPK activation, as well as PPARGC1A and ESRRA expression." (PMID 32121253, 2020). "Taken together, our findings suggest that intestinal ESRRA does not govern resistance to HFD-induced obesity and supports investigation in other tissues to define the functions of ESRRA in diet-induced obesity." (PMID 39826697, 2025). "Interestingly, while we again observed resistance to HFD-induced obesity in Esrra−/− mice, the intestine-specific mutants did not exhibit resistance to obesity, suggesting ESRRA in the intestine does not contribute to diet-induced weight gain." (PMID 39826697, 2025). "Similarly, ESRRA null mice are resistant to developing high fat-induced obesity without altering the energy expenditure." (PMID 32121253, 2020).
endometrial cancer (24 papers, 2016 to 2025). Primary or metastatic malignant neoplasm involving the endometrium (mucous membrane that lines the endometrial cavity). "TGF-β is associated with increased migration and malignant transformation of endometrial carcinomas through activation of estrogen-related receptor alpha (ERRα); it is also associated with invasion and epithelial-to-mesenchymal transition (EMT)." (PMID 36291839, 2022). "Estrogen-related receptor alpha (ERRα), which shares structural similarities with estrogen receptors, is associated with tumor progression in endometrial cancer, but little is known about the detailed underlying mechanism." (PMID 31040369, 2019). "We previously reported that the overexpression of estrogen-related receptor alpha (ERRα) promotes endometrial cancer (EC) invasion and metastasis." (PMID 37864196, 2023). "Estrogen-related receptor alpha (ERRα) plays an important role in endometrial cancer (EC) progression." (PMID 36835419, 2023). "Estrogen-related receptor alpha (ERRα) is significantly elevated in endometrial cancer tissues, especially with nodal metastasis and can directly bind to promoter of TGF-β1 and increase its transcription." (PMID 34951691, 2022). "Estrogen-related receptor alpha (ERRα), a central regulator of cellular energy metabolism linked to poor cancer prognosis, enhances glycolytic metabolism and targets the NLRP3/caspase-1/GSDMD pathway to regulate pyroptosis in endometrial cancer." (PMID 40718836, 2025). "Recently, they discovered that ESRRA could be a target of TGF-β to promote epithelial–mesenchymal transition in endometrial cancer." (PMID 32549787, 2020).
ovarian carcinoma (22 papers, 2011 to 2024). A malignant neoplasm originating from the surface ovarian epithelium. "In ovarian cancer, ESRRA expression has also been associated with decreased survival, and kaempferol, which inhibits angiogenesis by ovarian cancer cell lines, acts at least partially by decreasing ESRRA expression." (PMID 21949640, 2011). "Very recently, the ESRRA locus has been implicated in increased risk of ovarian cancer." (PMID 21949640, 2011). "In the case of ovarian cancer, the expression level of ESRRA is known to serve as a biomarker for the disease, as its expression profile correlates with serum CA-125 levels." (PMID 26639757, 2015). "We assessed 163 similar ovarian carcinomas for the presence of the ESRRA–C11orf20 fusion transcript, plus a further 67 ovarian carcinomas of different histologic subtypes/grades, to see if these tumors were characterized by the same fusion." (PMID 24504521, 2014). "Many ovarian cancers have a chromosomal rearrangement that fuses two neighboring genes, ESRRA and c11orf20." (PMID 21949640, 2011). "Data from high-throughput sequencing of 23 ovarian carcinomas were screened in search of alternative partner(s) for the ESRRA and/or C11orf20 gene, but none was found." (PMID 24504521, 2014). "In contrast to the chemerin protein data from IHC, mRNA levels of the RARRES2 gene in ovarian cancer were not correlated with PGR, ESR2, ESRRA, ESRRB, ESRRG, nor CEACAM5 after analysis of both patient collectives on the mentioned platforms (p > 0.05 for all)." (PMID 36900088, 2023).
breast tumors (21 papers, 2009 to 2026). "In addition, ESRRA was downregulated in breast tumors but upregulated in the other tumors, and ESRRB and ESRRG were upregulated in breast, ovarian, and endometrial tumors." (PMID 38582811, 2024).
diabetes (19 papers, 2013 to 2026). "An evidence demonstrating a role for ESRRA (estrogen related receptor alpha) and THRAP3 in diabetes, but these genes might be liable for development of HF." (PMID 34218797, 2021).